FFAR4 (free fatty acid receptor 4)
Description:
[Isoform 2]: G protein-coupled receptor for long-chain fatty acids (LCFAs) with a major role in adipogenesis, energy metabolism and inflammation. Signals via G protein and beta-arrestin pathways. LCFAs sensing initiates activation of phosphoinositidase C-linked G proteins GNAQ and GNA11 (G(q)/G(11)), inducing a variety of cellular responses via second messenger pathways such as intracellular calcium mobilization, modulation of cyclic adenosine monophosphate (cAMP) production, and mitogen-activated protein kinases (MAPKs). After LCFAs binding, associates with beta-arrestin ARRB2 that acts as an adapter protein coupling the receptor to specific downstream signaling pathways, as well as mediating receptor endocytosis. In response to dietary fats, plays an important role in the regulation of adipocyte proliferation and differentiation (By similarity). Acts as a receptor for omega-3 polyunsaturated fatty acids (PUFAs) at primary cilium of perivascular preadipocytes, initiating an adipogenic program via cAMP and CTCF-dependent chromatin remodeling that ultimately results in transcriptional activation of adipogenic genes and cell cycle entry (By similarity). Induces differentiation of brown adipocytes probably via autocrine and endocrine functions of FGF21 hormone (By similarity). Activates brown adipocytes by initiating intracellular calcium signaling that leads to mitochondrial depolarization and fission, and overall increased mitochondrial respiration (By similarity). Consequently stimulates fatty acid uptake and oxidation in mitochondria together with UCP1-mediated thermogenic respiration, eventually reducing fat mass (By similarity). Regulates bi-potential differentiation of bone marrow mesenchymal stem cells toward osteoblasts or adipocytes likely by up-regulating distinct integrins (By similarity). In response to dietary fats regulates hormone secretion and appetite (By similarity). Stimulates GIP and GLP1 secretion from enteroendocrine cells as well as GCG secretion in pancreatic alpha cells, thereby playing a role in the regulation of blood glucose levels (By similarity). Negatively regulates glucose-induced SST secretion in pancreatic delta cells (By similarity). Mediates LCFAs inhibition of GHRL secretion, an appetite-controlling hormone (By similarity). In taste buds, contributes to sensing of dietary fatty acids by the gustatory system (By similarity). During the inflammatory response, promotes anti-inflammatory M2 macrophage differentiation in adipose tissue (By similarity). Mediates the anti-inflammatory effects of omega-3 PUFAs via inhibition of NLRP3 inflammasome activation. In this pathway, interacts with adapter protein ARRB2 and inhibits the priming step triggered by Toll-like receptors (TLRs) at the level of TAK1 and TAB1 (By similarity). Further inhibits the activation step when ARRB2 directly associates with NLRP3, leading to inhibition of pro-inflammatory cytokine release. Mediates LCFAs anti-apoptotic effects (By similarity). Mediates VLCFAs-dependent liver-to-adipose tissue signaling and adipose tissue thermogenesis. [Isoform 1]: Receptor for LCFAs decoupled from G protein signaling. May signal through beta-arrestin pathway. After LCFAs binding, associates with beta-arrestin ARRB2 that may act as an adapter protein coupling the receptor to specific downstream signaling pathways, as well as mediating receptor endocytosis.
Synonyms: GPR120; GPR129; O3FAR1; PGR4; BMIQ10; GT01; OB10Q
Tractability: Small molecule: a structure with a bound ligand is known; a high-quality ligand is known; it belongs to a druggable protein family. Antibody: UniProt places it where antibodies can reach, with high confidence; its Gene Ontology location is reachable by antibodies, with high confidence; UniProt predicts a signal peptide or a membrane-spanning region; the Human Protein Atlas places it where antibodies can reach. PROTAC: a small molecule that binds it is known.
Target class: Family A G protein-coupled receptor; Small molecule receptor (family A GPCR); Membrane receptor; Free fatty acid receptor; Lipid-like ligand receptor (family A GPCR)
Chemical probes: AH 7614, GPR120-IN-1 (high quality), TUG-891
Gene: Protein-coding gene on chromosome 10 (93,566,665 to 93,604,480, forward strand). Ensembl gene ENSG00000186188.
Subcellular location: Cell membrane (Isoform 1); Endosome membrane; Lysosome membrane; Cell membrane (Isoform 2); Cell projection, cilium membrane
Subcellular location (Human Protein Atlas): Plasma membrane; Basal body; Vesicles
Pathways (Reactome):
Signal Transduction: Free fatty acid receptors; G alpha (q) signalling events
Metabolism of proteins: Synthesis, secretion, and inactivation of Glucagon-like Peptide-1 (GLP-1)
Gene Ontology:
Molecular function: fatty acid binding; G protein-coupled receptor activity; taste receptor activity
Biological process: negative regulation of interleukin-1 beta production; white fat cell differentiation; adenylate cyclase-activating G protein-coupled receptor signaling pathway; brown fat cell differentiation; G protein-coupled receptor signaling pathway; ghrelin secretion; hormone secretion; negative regulation of apoptotic process; negative regulation of cytokine production; negative regulation of inflammatory response; negative regulation of somatostatin secretion; positive regulation of cold-induced thermogenesis; positive regulation of ERK1 and ERK2 cascade; positive regulation of glucagon secretion; positive regulation of osteoblast differentiation; regulation of D-glucose transmembrane transport; detection of chemical stimulus involved in sensory perception of taste; fat cell differentiation; phospholipase C-activating G protein-coupled receptor signaling pathway; positive regulation of brown fat cell differentiation; positive regulation of cytosolic calcium ion concentration
Cellular component: cilium; endosome membrane; lysosomal membrane; plasma membrane; ciliary membrane; endocytic vesicle; membrane
Genetic constraint (gnomAD): Loss-of-function variants: 19 observed, 26.95 expected, observed/expected ratio (o/e) 0.71, 90% interval 0.49 to 1.03. The synonymous counts are far from expectation, so gnomAD's model fits this gene poorly and the ratio says little. Missense variants: 476 observed, 468.44 expected, observed/expected ratio (o/e) 1.02, 90% interval 0.94 to 1.1. Synonymous variants: 254 observed, 207.94 expected, observed/expected ratio (o/e) 1.22, 90% interval 1.1 to 1.36.
Homologues: Orthologues: chimpanzee FFAR4 (99% identical), macaque FFAR4 (98% identical), dog FFAR4 (88% identical), pig FFAR4 (88% identical), rabbit FFAR4 (87% identical), mouse Ffar4 (86% identical), rat Ffar4 (85% identical), guinea pig FFAR4 (83% identical), Drosophila melanogaster CrzR (20% identical), Caenorhabditis elegans daf-38 (17% identical). Paralogues in human: CCKAR (25% identical), GALR1 (24% identical), NPFFR1 (22% identical), HCRTR2 (21% identical), OXTR (21% identical), AVPR1A (20% identical), CCKBR (20% identical), HCRTR1 (20% identical), QRFPR (20% identical), AVPR1B (19% identical), NPFFR2 (19% identical), GALR3 (18% identical), and 4 more.
Diseases named in the same sentence as FFAR4 in open-access papers:
FFAR4 is named in the same sentence as 122 diseases in open-access papers, as found by Europe PMC text mining. Sharing a sentence is not in itself a finding about the gene and the disease. The quoted sentences say what the papers report.
Obesity (104 papers, 2012 to 2026). Accumulation of substantial excess body fat. "As expected from its roles, FFAR4-deficiency increased obesity upon high-fat-diet feeding and resulted in IR and hepatic fat accumulation with impaired insulin signaling activity and increased inflammation in adipose tissues." (PMID 40427589, 2025). "Nonetheless, our results indicate that loss of Ffar4 induced 15% more weight gain over 20 weeks in female mice, suggesting that Ffar4 attenuates obesity in females." (PMID 37075982, 2023). "Third, mice deficient in FFAR4 are more likely to develop obesity, metabolic dysregulation, and insulin resistance, as well as increased inflammation in adipose tissue." (PMID 35203397, 2022). "PUFAs can be metabolized into lipid mediators, or can act through free fatty acid receptor 4 (FFAR4, also termed GPR120).GPR120 deficiency causes obesity in mouse and human, due to increased adipocyte differentiation and lipogenesis in the liver." (PMID 34827703, 2021). "In humans, a deleterious non-synonymous mutation (p.R270H) that inhibits FFAR4 signaling was found to associate with increased risk of obesity in a European population." (PMID 30190473, 2018). "Of note, development of severe obesity, liver fat accumulation, and insulin resistance in FFAR4-deficient mice under high-fat diet were accompanied by lower SCD1 gene expression." (PMID 30190473, 2018). "FFAR4 KO mice develop glucose intolerance, and a dysfunctional variant of FFAR4 (R279H) is associated with obesity in humans." (PMID 30061862, 2018). "Compared to wild-type mice, high-fat fed FFAR4-deficient mice developed more severe obesity, liver fat accumulation, and insulin resistance." (PMID 30190473, 2018). "It has been shown that a particular SNP of FFAR4, rs116454156, is associated with obesity and insulin resistance in obese Europeans." (PMID 29113108, 2017). "Human obesity has been associated with altered FFAR4 expression in adipose tissue, involving a deleterious Ffar4 mutation that is unable to transduce LCFA binding." (PMID 26258126, 2015). "Recently, we found and reported that gene deficiency and dysfunction of Ffar4 lead to obesity in both mice and humans." (PMID 25414667, 2014). "Furthermore, a detrimental variant of FFAR4 (p.R270H) has been linked to elevated fasting glucose levels and an increased risk of obesity." (PMID 40005862, 2025). "In humans, a non-synonymous mutation of FFAR4 associated with obesity whereas global knockout of FFAR4 in HFD mice led to weight gain, glucose intolerance, fatty liver, and insulin resistance, suggesting that intact FFAR4 signaling is critical for maintaining systemic glucose homeostasis." (PMID 37484954, 2023). "Interestingly, in humans, the polymorphism R270H in at codon 270 (FFAR4, p.R270H, rs116454156) is described as a risk factor for obesity." (PMID 36831123, 2023). "In addition, a deleterious variant of FFAR4 (R270H) is associated with an increased risk of obesity and increased fasting glucose levels in human subjects of European origin." (PMID 35203397, 2022). "Missense variant rs116454156 A of the FFAR4 gene is associated with a higher risk of obesity." (PMID 34834553, 2021). "The relative abundance of FFAR-4 mRNA is associated with obesity in human adipose tissues, which might be increased as a result of the oxidation of lipids." (PMID 32574225, 2020). "FFAR4 plays protective roles in metabolic disease and dysfunction of FFAR4 has been shown to contribute to insulin resistance and obesity in both humans and mice." (PMID 40157537, 2025). "For instance, GPR120 (FFAR4) activation enhances insulin sensitivity and promotes anti-inflammatory responses in adipocytes, which is particularly important in the context of obesity and insulin resistance." (PMID 41048440, 2025). "It has been demonstrated that the expression of FFAR4 in adipose tissue is markedly elevated in individuals with obesity in comparison to those with a normal BMI." (PMID 40005862, 2025).
Obesity (continued). "FFAR4 has received special attention in the context of chronic inflammatory diseases, including atherosclerosis, obesity and NAFLD, through to its anti-inflammatory effect." (PMID 34575934, 2021). "Many studies have shown that FFAR4 plays an important role in the treatment of diabetes, obesity, liver damage and other immune diseases." (PMID 34177969, 2021). "Accordingly, we posit that free fatty acid receptors (FFAR1 and FFAR4) can modulate E–C coupling in HASM cells and play a role in obesity-associated AHR." (PMID 33256729, 2020). "The gene encoding this protein is known as GPR120/FFA4/FFAR4, and coding mutations in the gene have been associated with human obesity." (PMID 33233816, 2020). "Ffar4, known as GPR120, promotes adipogenesis via PPARγ but also attenuates low-grade inflammation and insulin resistance accompanying obesity." (PMID 31208033, 2019). "Contradicting the majority of existing literature, recent evidence suggests that FFAR4 is dispensable for the beneficial effects of ω3-PUFAs on HFD-induced obesity, whereas the anti-inflammatory nature of FFAR4 remains largely unchallenged." (PMID 27999451, 2016). "Although these findings suggest a pro-adipogenic function of FFAR4, FFAR4-deficient mice are actually more prone to diet-induced obesity than wild type littermates, consistent with an anti-obesity function of FFAR4." (PMID 25076939, 2014). "We found that HFD-fed Ffar4 KO mice developed severe obesity, which was accompanied by decreased differentiation and lipogenesis in adipocytes." (PMID 25414667, 2014). "Given this evidence, the present trial aimed to assess whether marine ω-3 PUFA supplementation enhances FFAR4 activation in PBMCs and thereby contributes to the reduction in inflammatory markers in individuals with obesity." (PMID 41373925, 2025). "Chronic systemic inflammation, aging, and obesity have been reported to downregulate FFAR4 expression in osteoclasts and osteoblasts, which may impair the anti-inflammatory and bone-protective actions of DHA in such conditions." (PMID 40807354, 2025). "However, some controversy exists, as reduced expression of GPR120/FFAR4 has been documented in cases of extreme obesity and IR in children." (PMID 40141148, 2025). "While FFAR4 is best known for its protective role in obesity and diabetes, recent studies have demonstrated that FFAR4 may also prevent the development of atherosclerosis and cardiovascular disease." (PMID 40157537, 2025). "Taken together, these findings suggest that the clinical effects of FFAR4 treatment might be used not only for disorders such as type 2 diabetes and obesity but also the inhibition of osteoclast differentiation and activity." (PMID 38263167, 2024). "An increasing number of studies suggested that FFAR4 may be a potential therapeutic target for metabolic diseases such as DM and obesity." (PMID 39519029, 2024). "In summary, the loss of Ffar4 in females resulted in greater obesity in response to the HFpEF-MetS diet but this had no worsening effect on cardiac function as was observed in male Ffar4KO mice." (PMID 37075982, 2023). "In macrophages, Ffar4 activation inhibits NFkB signaling and subsequent production of the inflammatory cytokines interleukin-6 and TNFα, rendering these macrophages less inflammatory and attenuating adipocyte dysfunction in obesity." (PMID 37075982, 2023). "Ablation of the Ffar4 gene in mice leads to obesity, glucose intolerance and hepatic steatosis." (PMID 34195966, 2022). "Collectively, how changes associated with an obesity phenotype, such as inflammation, proliferation and cell metabolism, are differentially modulated by FFAR1 or FFAR4 in obesity remains unknown." (PMID 33256729, 2020). "FFAR4 is also thought to be involved in the development of obesity in mice and humans." (PMID 29113108, 2017). "Thus, activation of FFAR4 has been reported to ameliorate chronic low-grade inflammation and insulin resistance accompanying obesity." (PMID 27999451, 2016).
Obesity (continued). "Additionally, a lack of FFAR4 signaling activity due to a genetic mutation is correlated with increased risk of obesity." (PMID 40427589, 2025). "Therefore, FFAR4 is an essential target in the treatment of DM, inflammation, and obesity." (PMID 39519029, 2024). "Interestingly, it has also been shown that FFAR4 stimulation may result in a beneficial phenotypical switch between M1/M2 macrophages infiltrating adipose tissue in obesity." (PMID 34575934, 2021). "Our hypothesis based on preexisting biological information was that FFAR4 would show a strong association with dichotomized obesity phenotype, but in fact just testing FFAR4 would not result in a significant finding." (PMID 33240333, 2020). "Furthermore, FFAR4 expression in macrophages is induced upon obesity." (PMID 25076939, 2014). "This suggests the potential for FFAR4 activation to extend from monocytes to resident adipose tissue macrophages, which could have implications in promoting pro-resolving mechanisms and improving insulin sensitivity, thereby modulating the inflammatory response in obesity." (PMID 41373925, 2025). "Treatment of adipocytes with agonists TUG-891 (selective for the FFAR4) and GW9508 (selective for FFAR1/GPR40) induce deoxyglucose uptake, thus indicating a promising role to counteract obesity and insulin resistance." (PMID 36831123, 2023). "While these results clearly demonstrate a critical role of FFAR4 in the protective effects on obesity and CMDs, other studies showed that FFAR4 is not needed for the anti-inflammatory and insulin-sensitizing effects of n-3 PUFAs." (PMID 40427589, 2025). "Similar to GPR40, other closely related G-protein-coupled receptors like GPR109A and GPR120 (also called FFAR4), have also been shown to bind medium- and long-chain fatty acids (e.g., ω-3 DHA and EPA) and produce beneficial effects in diabetes and obesity." (PMID 39683565, 2024). "A lot of studies focused on GPR120, also named Free Fatty Acid Receptor 4 (FFAR4; UniProt ID Q5NUL3), being an interesting drug target for the management and treatment of a series of disorders including Type 2 diabetes mellitus, obesity and those related to the sense of satiety." (PMID 38496766, 2024). "In knockout animals on an HFD, opposite effects of these FFARs have been registered: the absence of the Ffar4 gene enhances obesity and inflammation, whereas the absence of the Ffar2 gene diminishes weight and suppresses the migration of macrophages in mice." (PMID 34834553, 2021). "We therefore asked if Ffar4 KO mice in the current study would develop insulin resistance in the absence of obesity." (PMID 27999451, 2016). "Here we show that feeding mice a high dose of ω3-PUFAs protects against HFD-induced obesity, steatosis, insulin resistance, and visceral adipose tissue inflammation independent of FFAR4 status." (PMID 27999451, 2016). "Taken together, the studies of humans lacking functional FFAR4 and Ffar4 KO mice indicate that dysfunction of FFAR4 leads to obesity in both mice and humans." (PMID 25414667, 2014). "First, we identified gene sets related to the function of each obesity-related serum factor: HG/HI (Insr, Irs1, Rps6kb1, Slc2a4, Slc2a5, Slc2a1), TNF-α (Tnfrsf1a, Tradd, Traf2, Fadd), IL-6 (Il6ra, Il6st, Jak1), and fatty acids (PA, LA, Chol; Ffar1, Ffar4, Ppara, Pdk4, Pgc1a)." (PMID 37047207, 2023).